AHR (aryl hydrocarbon receptor)
Diseases named in the same sentence as AHR in open-access papers (continued):
Sharing a sentence is not in itself a finding about the gene and the disease.
infection (continued). "Several AhR antagonists, such as CH-223191 and Stem Regenin 1, have been identified; however, their therapeutic value against IV-infection-induced LI is unclear." (PMID 32689931, 2020). "The activation of the AhR, which occurs via kynurenine mediation, regulates the production of IFNβ negatively after IV infection, which allows virus propagation." (PMID 32689931, 2020). "In contrast, the reduced numbers of ILC3 at the site of infection of AhR−/−, showed that these cells are much more dependent on AhR activity than Th17 cells." (PMID 32647342, 2020). "The influence of AhR on the fungal burden, recovered 96 h, 2 and 10 weeks after infection with 1 × 106P." (PMID 32647342, 2020). "To ascertain the transient nature of AhR agonist single treatment- induced differences in lesional Tnf expression, we also measured Tnf expression in the skin after 3w of infection." (PMID 31749794, 2019). "Perhaps activation of AhR signaling at the peak of infection is protective against L. intracellularis infection and contributes to the resolution of lesions with time." (PMID 30696739, 2019). "Promoter analysis revealed that AhR:Arnt plays an important role in induction of gga-miR-451 transcription upon MG-HS infection." (PMID 31238581, 2019). "To further explore the role of AhR:Arnt upon MG-HS infection, we measured the expression of AhR:Arnt in MG-HS-infected DF-1 cells." (PMID 31238581, 2019). "In summary, in this study, we demonstrated that normal cellular and molecular pathways mediated by AHR were used by HIV-1 to promote infection and viral reactivation and that Trp metabolites augmented the efficiency of this process." (PMID 31848275, 2019). "Lower levels of gD protein were observed in AhR activated macrophages compared to control cells, with the most pronounced differences occurring at 12 hr post infection." (PMID 30132758, 2018). "Measurement of plaque forming units (PFU) in culture supernatants revealed that progeny viral yield was decreased in AhR activated macrophages by 12-fold at 24 hr post infection." (PMID 30132758, 2018). "The importance of AhR-driven changes in host responses to infection includes the potential for environmentally derived AhR ligands to affect host defense mechanisms during infection." (PMID 30510489, 2018). "Being endowed with the ability to both promote and restrain immune activation, AhR is well positioned to exert pathogen control and disease tolerance during infection." (PMID 30510489, 2018). "Recent studies have identified the molecular functions of AhR in the immune system during steady state and during infection and inflammation." (PMID 30283437, 2018). "(D) Single round virus replication in macrophages treated with SIV3+ or SIV3+ ΔVpx virus like particles and AhR agonist or antagonist before infection with HIV-1NLYU2-nluc." (PMID 30132758, 2018). "We found that regeneration of intestinal epithelial cells (IECs) upon injury through infection or chemical insults was profoundly influenced by the environmental sensor aryl hydrocarbon receptor (AHR)." (PMID 30119997, 2018). "The role of AHR pathway has been characterized in response to infection with BCG, however our results provide additional motivation for further investigation into this pathway." (PMID 27055235, 2016). "We specifically examined CD4+ T cells, and observed that early-life AhR activation changed the proportion of functionally distinct CD4+ T-cell subsets responding to infection." (PMID 25051576, 2014). "Using AhR+/– dams, we confirmed that the presence of the AhR was required in the offspring in order for maternal treatment with TCDD to alter the CD4+ T-cell response to infection." (PMID 25051576, 2014). "We found here that NKp46+ cells expanded in the vagina in infection and produced IL-22, more than IL-17A, likely via AhR." (PMID 23853597, 2013).
infection (continued). "Differential expression of pathways associated with cellular growth and proliferation such as mTOR signaling and aryl hydrocarbon receptor signaling are also enriched following infection with both strains." (PMID 23516652, 2013). "For example, with influenza A virus infection AhR activation by the administration of TCDD decreased the survival time to lethal infection and resulted in mortality with a non lethal dose of the virus." (PMID 22174686, 2011). "Our data indicate that prolonged AHR activation caused toxic endpoints for liver and thymus but was not per se interfering with the host response to infection with the intestinal pathogen C.rodentium." (PMID 40502009, 2025). "Furthermore, the targeted deletion of the AHR from intestinal epithelial cells also led to reduced resistance to infection in the colon." (PMID 40077746, 2025). "Here, IDO1‐mediated kynurenine production and the AHR activation pathway were shown to impair P. aeruginosa infection by interfering with bacterial phagocytosis and preventing neutrophil recruitment to the infection site." (PMID 40387573, 2025). "In infection, AHR can modify natural immunological reactions to various pathogens, including CoVs like Middle East respiratory syndrome coronavirus (MERS-CoV), mouse hepatitis virus (MHV), human coronavirus (HCoV) 229E, HCoV-OC43, SARS-CoV-1, SARS-CoV-2, and CCoV-II." (PMID 39985684, 2025). "Notably, AhR has been shown to be up-regulated during infection with several coronaviruses, including Middle East respiratory syndrome coronavirus, human coronavirus (HCoV) 229E, HCoV-OC43, SARS-CoV-1, SARS-CoV-2, MHV and CCoV-II." (PMID 41012698, 2025). "Our data indicate that prolonged AHR activation caused toxic endpoints for liver and thymus but was not per se interfering with the host response to infection with the intestinal pathogen C." (PMID 41057229, 2025). "To evaluate the impact of prolonged AHR activation on the host response we infected mice with the intestinal pathogen C. rodentium which is a widely used model organism to study pathology as well as the host response to infection." (PMID 40502009, 2025). "The role of AhR extends beyond its involvement in pathogen infection, encompassing immune system regulation such as the promotion of Treg cell generation, mediation of autophagy-related neurotoxicity, regulation of circadian rhythm, and initiation of carcinogenesis processes." (PMID 38680494, 2024). "Previous research indicates that AhR may limit parasite replication and infection outcome by functioning as a ligand-activated transcription factor in various regulatory pathways." (PMID 38680494, 2024). "In PI-IBS, there is a notable reduction in SCFA production and an exacerbation of intestinal inflammation, leading to decreased tryptophan production in the later stages of infection, significant decline in the indole pathway, and diminished aryl hydrocarbon receptor (AhR) activity." (PMID 39766350, 2024). "AhR signaling is a common host response to infection by multiple coronaviruses." (PMID 38474725, 2024). "However, we observed a trend toward enhanced HCov-229E infection relative to cell viability which is in line with the notion that the activators of AHR and NFE2L2 were antiviral." (PMID 38319076, 2024). "AHR activation by ligands can induce the immune system’s development: controlling gene expression and DNA methylation as T-cells react to infection later in life AHR CD4+CD8α α+ double positive intraepithelial lymphocytes (DP IELs) which display a significant role in tolerance to dietary antigens." (PMID 38542367, 2024). "This review focuses on the crucial role of the AhR in facilitating and limiting the proliferation of pathogens, specifically in relation to the host cell type and the species of etiological agents involved in microbial pathogen infections." (PMID 38680494, 2024). "This review mainly discusses the role of AhR in inflammation and infection." (PMID 38680494, 2024).
infection (continued). "Supporting the importance of AhR in IECs, AhR-deficient mice or mice lacking AhR specifically in IECs were more susceptible to infection with the gram-negative bacterium Citrobacter rodentium." (PMID 36875083, 2023). "Finally, we show that protective AHR signalling in lung endothelial cells is dampened by the infection itself." (PMID 37587341, 2023). "We found that 5-HT produced by mast cells essentially contributed to pathogen clearance and immune homeostasis in infection by promoting the host protective indoleamine-2,3-dioxygenase 1/kynurenine pathway and limiting the microbial activation of the indole/aryl hydrocarbon receptor pathway." (PMID 37717018, 2023). "Considering the protective role AHR plays in lung vessels, we hypothesised that infection-induced perturbation of the AHR response may dampen protective signalling in endothelia." (PMID 37587341, 2023). "Finally, dietary supplementation of the AHR pro-ligand indole-3-carbinol in newborn mice promotes resistance to infection." (PMID 38052207, 2023). "Currently, there is increasing evidence supporting that the aryl hydrocarbon receptor (AHR) is an important modulator of the host immune response and this feature contributes to the differential clinical outcomes of infections at the individual and population level." (PMID 36851583, 2023). "AHR deficiency reduces CD8+ IELs, decreases their cytotoxicity, and worsens infection." (PMID 38052207, 2023). "Interestingly, we find diet-dependent lung AHR activity to be dampened by the infection itself, suggesting that infection-induced alterations in dietary metabolism or consumption affect lung function via AHR." (PMID 37587341, 2023). "AHR expression was also lower in patients with active infection." (PMID 37403036, 2023). "Indeed, both alphacoronavirus (H-CoV-229E and CCoV) and betacoronavirus (MCoV, MERS-CoV, SARS CoV-1 and SARS-CoV-2) up-regulate AhR during infection in vitro, indicating AhR as a feasible target for antiviral therapy." (PMID 37627739, 2023). "Recently, it was demonstrated that AhR is activated by infection with different coronaviruses and that pharmacological inhibition of AhR suppresses the in vivo replication of the viruses HCoV-229 and SARS-CoV-2, the causative agents of the common cold and COVID-1918." (PMID 37169746, 2023). "Therefore, the level of indole pyruvate reduction negatively modulates AhR activity in leukocytes that display IgGm+ for spike-S1 antigen at 60–90 days after infection." (PMID 36635345, 2023). "The AhR-mediated immune tolerant state caused by LPS stimulation protected the host against Gram-negative and Gram-positive pathogen infections, which suggests the essential role of AhR activation in inflammatory diseases." (PMID 35727038, 2022). "Notably, inflammatory stimuli affect Trp metabolism and AhR activation, which negatively regulate infection or inflammatory injury and maintain host mucosal homeostasis." (PMID 35727038, 2022). "In the case of infections, AhR activation appears to be a double-edged sword." (PMID 35203386, 2022). "Thus, AhR induces multiple regulatory pathways that ultimately affect parasite replication and infection outcomes." (PMID 36110860, 2022). "This implies that AhR activation in the infection context may mediate the transcriptional regulations of a negative loop to maintain an immune balance." (PMID 35397616, 2022). "Hence, the observed enhancement of S.E.-antigen-induced IL-10 production of immune cells at the site of infection, as well as systemically in the spleen, through BaP was AhR-dependent." (PMID 35203386, 2022). "Activation of AhR by CoV may change disease phenotypic features based on time after infection but also on diet and environmental factors." (PMID 33916409, 2021). "Thus, the proper targeting of AhR in the lung alleviates the inflammatory response during infection." (PMID 33916409, 2021).
infection (continued). "The activation of AHRs by CoVs may lead to a diverse set of phenotypic disease scenarios depending on the time after infection, overall state of health, hormonal balance, age, gender, co-morbidities, diet and environmental factors modulating AHR signaling." (PMID 33746961, 2021). "Different Kyn derivatives may act as ligands for AhR, and their dynamics differentiates the Mf and Mm hosts during infection." (PMID 35242812, 2021). "AhR activation has an overall anti-inflammatory and immunoregulatory role in innate and adaptative immunity, both in steady-state or in inflammatory scenarios such as autoimmunity or infection." (PMID 34093534, 2021). "Hence, based on our finding of increased AHR signaling in response to infection with multiple CoVs, we investigated the effect of AHR inhibition by the AHR antagonist CH22319149 on the replication of HCoV-229E and SARS-CoV-2 in vitro." (PMID 34446714, 2021). "Indeed, we also detected increased expression of AHR-pathway genes, suggesting increased AHR signaling, in available gene expression datasets of infection with M-CoV23, HCoV-229E24, MERS-CoV25, and SARS-CoV-122." (PMID 34446714, 2021). "Qiu and colleagues (2012) found that AHR-deficient ILCs lack the IL-23 receptor (IL-23R) and that AHR KO mice express IL-22 at reduced levels and, unlike wild-type mice, succumb to infection with C. rodentium." (PMID 32784381, 2020). "Since IPA phenocopies the anti-inflammatory effect of kynurenine via AhR and exhibits antimycobacterial properties, IPA could modulate the Trp-IDO-AhR axis to influence infection outcome to the benefit of the host in TB-IRIS management." (PMID 33193190, 2020). "As expected, only WT mice expressed AhR+ cells that increased in the course of infection." (PMID 32647342, 2020). "The levels of pulmonary NO after 96 h, 2 and 10 weeks of infection was also higher in AhR−/− mice, indicating that fungicidal ability in the absence of AhR is reduced, despite increased levels of nitric oxide that is considered a major P. brasiliensis fungicidal mediator of phagocytic cells." (PMID 32647342, 2020). "Decrease host resistance to a variety of infectious agents has been reported when TCDD exposure occurs prior to infection, however, whether the AhR ligation contributes to improve or worsen host resistant depends on the pathogen." (PMID 30984194, 2019). "Thus, AhR induce diverse regulatory pathways that finally impacts on parasite replication and infection outcome." (PMID 30984194, 2019). "It is important to note that AHR acts as an important co-factor in infections." (PMID 31001262, 2019). "Indeed, when we treated susceptible BALB/c mice with AhR agonist ITE at the first day of infection we observed a small, but significant reduction in footpad swelling during the first and third week of infection." (PMID 31749794, 2019). "Therefore, we injected BALB/c mice with AhR agonist ITE during infection with L. major and measured expression of genes using RT-PCR of foot skin samples after 20 h." (PMID 31749794, 2019). "Since we previously had demonstrated the relevance of the early cutaneous cytokine milieu for the subsequent development of resistance, we speculated that early AhR-dependent signaling also influences the course of infection." (PMID 31749794, 2019). "Therefore, we treated susceptible BALB/c mice with AhR agonist ITE, given as a single injection at the time of infection, reflecting its rapid induction in GMΦ of resistant mice." (PMID 31749794, 2019). "It has recently become known that AHR can be used by viruses to promote their infection." (PMID 31848275, 2019). "In such overview, tryptophan catabolism and production of indole-3-aldehyde by the commensal Lactobacillus reuteri has been shown to be able to inhibit the overgrowth of Candida albicans in mice gut by binding AhR and triggering the IL-22 pathway, thus protecting the mucosa from infection." (PMID 31475000, 2019).
infection (continued). "Most notably pathways associated with the Aryl Hydrocarbon Receptor (AhR), an important emerging modulator of inflammatory signaling, IL-17 and STAT3 associated signaling were more highly repressed or less activated during APEC O2-GFP infection." (PMID 31998322, 2019). "Moreover, we found AhR and Arnt were up-regulated in MG-HS infection, and AhR:Arnt decreased YWHAZ (14-3-3ζ ) expression probably through regulating gga-miR-451." (PMID 31238581, 2019). "Thus, AhR has pathway-specific roles that modulate host defense mechanisms during infection at least when AhR is tested in model high affinity ligands." (PMID 30510489, 2018). "This raises questions about whether other compounds that bind AHR will similarly dampen key host protective adaptive immune responses to infection." (PMID 29379138, 2018). "Although both types of chimeras eventually succumbed to infection, mice with Ahr deficiency in the non-hematopoietic compartment exhibited accelerated mortality, suggesting that AHR function is particularly important in IECs." (PMID 30119997, 2018). "In separate experiments, we observed that developmental AhR activation caused the same alterations in CD4+ T-cell responsiveness to infection in all three congenic strains of mice (data not shown)." (PMID 25051576, 2014). "Then, using reciprocal adoptive transfers, we evaluated whether CD4+ T-cell responses to infection were modulated via intrinsic or extrinsic effects of AhR activation during development on CD4+ T cells in adult mice." (PMID 25051576, 2014). "In the present study, we examined whether AhR activation during development changes the response of CD4+ T cells to infection with IAV later in life." (PMID 25051576, 2014). "However, no significant changes in Cb intracellular replication were observed in FICZ-treated THP-1 cells, suggesting that AHR’s role in the infection may involve modulation of multiple signaling pathways." (PMID 39711545, 2024). "Two very recent back-to-back papers published in Nature1,2 decipher the holistic role of the aryl hydrocarbon receptor (AHR)/dietary-ligand axis, in enteric and pulmonary vasculature to emphasize tolerance induction and vessel integrity during homeostasis, sterile inflammation and infections." (PMID 38388453, 2024). "Indeed, MC were found to accumulate 5-HT in infection via AhR." (PMID 37717018, 2023). "We resolve this apparent controversy and report that C. elegans strains lacking the ability to sense bacterial pigments through the aryl hydrocarbon receptor (AhR) are more susceptible to ΔPf4 infection compared to wild-type C. elegans capable of detecting bacterial pigments." (PMID 36800381, 2023). "AhR is a ligand-activated transcription factor that is vital for intestinal homeostasis by suppressing inflammation and by sustaining the epithelial barrier in the gastrointestinal tract, a rich source of AhR ligands, and to protect the gut upon infection or induced colitis." (PMID 36678175, 2023). "In the context of infection, we showed that effective clearance bacteria from the lungs of mice, as well as mitigation of bacterial dissemination was dependent on a balance of increased AhR activity and decreased TGF-β1 signaling, in-line with the previous results." (PMID 37886455, 2023). "Thus, in addition to platelets recruited in infection, MC produces 5-HT in the lung via AhR." (PMID 37717018, 2023). "Moreover, independent of infection, AhR-deficient aged mice show impaired intestinal differentiation and subclinical inflammation and are exceptionally prone to experimentally induced carcinogenesis." (PMID 37174049, 2023). "The human aryl hydrocarbon receptor (AhR) is present in the human gut and interacts with a wide array of microbial metabolites and was shown to detect and react to relative abundances of AHLs, quinolones and phenazines produced by P. aeruginosa to manage immune response over the course of infection." (PMID 36504831, 2022).